IQCH (IQ motif containing H)
Description:
May play a regulatory role in spermatogenesis.
Synonyms: FLJ12476; NYDSP5
Tractability: No criterion of Open Targets' tractability assessment is met for any kind of drug.
Gene: Protein-coding gene on chromosome 15 (67,254,786 to 67,502,260, forward strand). Ensembl gene ENSG00000103599.
Subcellular location (Human Protein Atlas): Cytosol; Mid piece; Vesicles
Gene Ontology:
Cellular component: nuclear speck
Genetic constraint (gnomAD): Loss-of-function variants: 53 observed, 77.35 expected, observed/expected ratio (o/e) 0.69, 90% interval 0.55 to 0.86. The upper end of that interval is the gene's LOEUF score, 0.86, which puts it in group 3 of 6, group 1 being the genes least tolerant of losing a copy. Missense variants: 796 observed, 945.63 expected, observed/expected ratio (o/e) 0.84, 90% interval 0.79 to 0.89. Synonymous variants: 306 observed, 349.35 expected, observed/expected ratio (o/e) 0.88, 90% interval 0.8 to 0.96.
Homologues: Orthologues: chimpanzee IQCH (99% identical), macaque IQCH (94% identical), dog IQCH (82% identical), rabbit IQCH (78% identical), mouse Iqch (74% identical), rat Iqch (71% identical), tropical clawed frog iqch (49% identical), zebrafish iqch (41% identical).
Diseases named in the same sentence as IQCH in open-access papers:
IQCH is named in the same sentence as 9 diseases in open-access papers, as found by Europe PMC text mining. Sharing a sentence is not in itself a finding about the gene and the disease. The quoted sentences say what the papers report.
asthenozoospermia (1 paper, 2026). "Specific loss-of-function mutations are strongly linked to distinct clinical phenotypes: IQUB variants to asthenozoospermia, IQCN mutations to total fertilization failure, and IQCH deficiency to azoospermia." (PMID 41602861, 2026). "Within the subset of cases with a genetic etiology, mutations in specific IQ motif genes have been established as monogenic causes for distinct phenotypes: IQUB (c.942T > G) with asthenozoospermia, IQCN (c.1061_1062delAT) with total fertilization failure, and IQCH variants with azoospermia." (PMID 41602861, 2026).
asthma (1 paper, 2021). "Among the shared genes, three genes, ITPR3, HEXIM1, and IQCH, were found to be reported in both GWASs of asthma and insomnia, and two genes, ITPR3 and HEXIM1 appear to be involved in the inflammation process." (PMID 34750467, 2021).
Azoospermia (1 paper, 2026). Absence of any measurable level of sperm,whereby spermatozoa cannot be observed even after centrifugation of the semen pellet. "In Europeans, preliminary WES of 500 non-obstructive azoospermia patients identified IQCH heterozygous variants (e.g., c.547G > A) with 1.2% frequency, potentially disrupting testis-specific RNA splicing." (PMID 41602861, 2026).
infertile (1 paper, 2024). "We believe that our findings will provide genetic diagnostic markers and potential therapeutic targets for infertile males with IQCH pathogenic variants." (PMID 39028117, 2024).
male infertility (1 paper, 2024). The inability of the male to effect fertilization of an ovum after a specified period of unprotected intercourse. "In this study, we identified a loss-of-function mutation in the novel gene IQ motif-containing H (IQCH) in a Chinese family with male infertility characterized by a cracked flagellar axoneme and abnormal mitochondrial structure." (PMID 39028117, 2024). "Taken together, these results reveal that this identified IQCH variant is responsible for splicing abnormalities and further causes a lack of IQCH expression, which is likely the genetic cause of male infertility in this family." (PMID 39028117, 2024). "Collectively, our findings unveiled a novel genetic diagnostic indicator of male infertility, and the uncovered mechanism of IQCH in spermatogenesis might shed new light on the treatment of this disease." (PMID 39028117, 2024). "Overall, this study revealed the function of IQCH, expanded the role of IQ motif-containing proteins in reproductive processes, and provided important guidance for genetic counseling and genetic diagnosis of male infertility." (PMID 39028117, 2024).
IQCH also shares sentences with these, for which no sentence is quoted: cardiovascular disorder (1 paper); insomnia (1); psychiatric disorder (1); Stroke (1).